IL4I1 (interleukin 4 induced 1)
Diseases named in the same sentence as IL4I1 in open-access papers (continued):
Sharing a sentence is not in itself a finding about the gene and the disease.
infection (continued). "Transcription of IL4I1 in the chicken cecum after oral infection of newly hatched chicken was similar to that of the majority of inducible genes, i.e. it reached its peak 4 days post-infection and then gradually decreased back to basal expression level." (PMID 32404145, 2020). "Finally, when we used real-time PCR for the verification of IL4I1 mRNA expression in the same samples as used for protein mass spectrometry, IL4I1 exhibited a 458× induction fold induction in the chicken cecum after the infection with wild-type S. Enteritidis." (PMID 32404145, 2020). "Thus, IL4I1 is induced by infection with various types of pathogens and may contribute to both the containment of the infectious agent and the limitation of the immunopathology mediated by effector Th1 or Th17 cells." (PMID 31330829, 2019). "Real-time PCR showed that IL4I1 expression in HD11 macrophages increased 5.42- and 40.72-fold 4 and 24 h after infection with wild-type S. Enteritidis, respectively." (PMID 32404145, 2020). "IL-4i1 deletion significantly reduced lung mycobacterial burden as early as 12 days after infection, while lung weights, free alveolar air spaces, and lung tissue pathology were not affected by the absence of IL-4i1." (PMID 34739044, 2021). "IL4I1 is phylogenetically related to fish LAAO, which have been shown to present antibacterial functions and accumulate in “granuloma-like” structures induced by the infection with larval nematodes." (PMID 23355881, 2013). "However, our results showed the DC populations from IL4I1-/- mice to be quantitatively similar to those of WT mice, with the exception of a slightly higher percentage of conventional DC2 at steady state and pDC at day 3 post-infection." (PMID 33343572, 2020).
bacterial infections (3 papers, 2013 to 2023). "A recent study showed that bacterial infection can induce IL4I1 expression." (PMID 36834576, 2023). "IL-4i1 is mainly expressed by antigen-presenting cells (APCs), inhibits T-cell proliferation, regulates B-cell activation, modulates T cell responses, and drives macrophage polarization, but its role in bacterial infections is understudied." (PMID 34739044, 2021). "In the context of bacterial infections, IL4I1 could be either secreted at the contact zone between the phagocytic cell and the bacteria, in the recently called “phagosomal synapse” or released in the phagolysosome, in both cases contributing to the bactericidal arsenal of the macrophage." (PMID 23355881, 2013).
IL4I1 also shares sentences with these, for which no sentence is quoted: breast adenocarcinoma (2 papers); colon cancer (2); colorectal cancer (2); mesothelioma (2); metastatic melanoma (2); non-small cell lung carcinoma (2); renal carcinoma (2); tuberculosis (2); adenocarcinoma (1); allergic disease (1); anaplastic astrocytoma (1); atherosclerosis (1); bladder urothelial carcinoma (1); cervical adenocarcinoma (1); cervical cancer (1); cholangiocarcinoma (1); chronic rhinosinusitis (1); clear cell renal carcinoma (1); coagulopathies (1); colon adenocarcinoma (1); COVID-19 (1); demyelination (1); dermatitis (1); fungal infection (1); Hypertension (1); insulin-dependent diabetes mellitus (1); intestinal neoplasm (1); lupus nephritis (1); Lymphatic Metastasis (1); mediastinal (1).
A further 12 diseases each share a sentence with IL4I1 in 1 paper.